ST3GAL1 (ST3 beta-galactoside alpha-2,3-sialyltransferase 1)
Diseases named in the same sentence as ST3GAL1 in open-access papers (continued):
Sharing a sentence is not in itself a finding about the gene and the disease.
melanoma (10 papers, 2020 to 2026). A malignant, usually aggressive tumor composed of atypical, neoplastic melanocytes. "Altogether, these data indicate that ST3GAL1 is consistently expressed in human melanomas and is associated with tumor progression." (PMID 33203881, 2020). "Moreover, in silico data analysis showed that ST3GAL1 is altered in 23% of human melanomas (missense mutations, gene amplification, or mRNA upregulation)." (PMID 33203881, 2020). "Our study suggests that targeting ST3GAL1-linked processes may become in the future a promising therapeutic approach to prevent or treat established melanoma metastasis." (PMID 33203881, 2020). "In melanoma, ST3GAL1 enhances dimerization and activation of the receptor tyrosine kinase AXL, increasing invasion and metastatic seeding." (PMID 41416421, 2026). "As one of the most studied ST3GAL members, ST3GAL1 is overexpressed in glioblastoma, melanoma, and estrogen receptor-positive breast cancer, through regulating cancer stemness, metastasis, angiogenesis, and tumor immune evasion." (PMID 36092699, 2022). "A recent study reported that ST3GAL1 expression correlates with melanoma progression and highlighted the critical role of ST3GAL1 in driving melanoma metastasis." (PMID 33921986, 2021). "A recent study from our group reported that the expression of the α 2,3-sialyltransferase ST3GAL1 correlates with melanoma progression and highlighted the critical role of ST3GAL1 in driving melanoma metastasis." (PMID 34440905, 2021). "Overall, these data reveal ST3GAL1 as a key downstream mediator that contributes to the aggressive behavior of melanoma cells induced by SOX2 and GLI1." (PMID 33203881, 2020). "In agreement with the identified role of ST3GAL1 in melanoma progression, ST3GAL1 is expressed at higher levels in metastastic compared to primary melanoma cases." (PMID 33203881, 2020). "In support of this regulation, a positive correlation between the expression of SOX2 and ST3GAL1 mRNA was observed in a panel of commercial and patient-derived melanoma cells." (PMID 33203881, 2020). "Both microarray dataset and immunohistochemistry show that ST3GAL1 expression is significantly higher in metastatic compared to primary melanomas." (PMID 33203881, 2020). "Here we report a mechanism regulated by the oncogenic SOX2-GLI1 transcriptional complex driving melanoma invasion through the induction of the sialyltransferase ST3GAL1." (PMID 33203881, 2020). "Based on these results, we focused on defining the functional role of the sialyltransferase ST3GAL1 in melanoma metastasis." (PMID 33203881, 2020). "Overall, our data suggest that sialylated AXL is a major mediator of the pro-metastatic role played by ST3GAL1 in melanoma." (PMID 33203881, 2020). "Taken together, our study reveals a functional SOX2/GLI1-ST3GAL1-AXL axis in a subgroup of melanomas involved in cancer progression, and highlights the therapeutic potential of targeting ST3GAL1 to prevent or treat metastatic melanoma." (PMID 33203881, 2020). "Consistently, ectopic expression of ST3GAL1 in SOX2- or GLI1-depleted SSM2c cells was able to rescue the decrease in melanoma cell invasion produced by SOX2 or GLI1 silencing." (PMID 33203881, 2020). "Our results showed that both GLI1 and SOX2 increased melanoma cell invasion and that depletion of ST3GAL1 was able to suppress the effects of both SOX2 and GLI1." (PMID 33203881, 2020). "As expected, ectopic expression of ST3GAL1 in A375 M6 and MeWo cells triggered a significant increase in melanoma cell invasion." (PMID 33203881, 2020). "Genetic silencing of ST3GAL1 reduces melanoma cell migration and invasion in vitro, whereas ST3GAL1 overexpression has the opposite effects." (PMID 33203881, 2020). "Our work indicates that the receptor tyrosine kinase AXL is a major mediator of the pro-invasive effects of ST3GAL1 in melanoma." (PMID 33203881, 2020).
melanoma (continued). "Consistently with transcriptomic data, immunohistochemical analysis of human melanoma tissue microarrays showed higher proportion of metastatic cases with medium/high ST3GAL1 staining compared to primary melanomas (p = 0.0198) or nevi (p = 0.0007)." (PMID 33203881, 2020). "Our data support a key role of the ST3GAL1-AXL axis as driver of melanoma metastasis, and highlight the therapeutic potential of targeting this axis to treat metastatic melanoma." (PMID 33203881, 2020). "ST3GAL1 staining in melanoma cells was observed in the cytoplasm with a perinuclear granular pattern (high magnification)." (PMID 33203881, 2020). "Our work provides the rationale for designing small molecules against ST3GAL1 and for drug repurposing to identify effective ST3GAL1 inhibitors for treatment of a subset of melanomas." (PMID 33203881, 2020). "MS analysis in a melanoma cell line derived from a metastasis (A375 M6) identified several putative ST3GAL1 substrates, with enrichment in proteins involved in cell migration, locomotion, motility, and adhesion, all processes relevant for tumor metastasis." (PMID 33203881, 2020). "Together our in vitro and in vivo data point toward several promoting effects of ST3GAL1 in melanoma progression, and provide strong evidence that silencing of ST3GAL1 inhibits the metastatic process in vivo." (PMID 33203881, 2020). "Silencing of ST3GAL1 substantially reduced the frequency of circulating melanoma cells in the blood and strongly inhibited the metastatic potential of A375 M6 cells, as shown by the reduced distribution of luminescence in organs such as lungs." (PMID 33203881, 2020). "Data mining of transcriptomic datasets from independent clinical cohorts revealed consistently higher levels of ST3GAL1 in melanoma compared to nevi and in metastatic cases compared to primary melanomas." (PMID 33203881, 2020). "We first examined how depletion of ST3GAL1 impacts on the ability of melanoma cells to survive and proliferate in a metastatic environment, using a model based on intracardiac instillation of melanoma cells." (PMID 33203881, 2020). "Similarly, upregulatory miRNAs targeting CD98hc (part of the amino acid transporter LAT-1), ST3GAL1, and ST3GAL2 are enriched in melanoma, forming a coregulatory network of the carrier protein CD98hc and the ST3GAL1/2 enzymes responsible for its sialylation." (PMID 40885395, 2025). "Besides p300, in melanoma, SOX2 forms a complex with GLI1 and cooperatively transactivates ST3GAL1, which promotes melanoma metastasis via upregulating AXL." (PMID 38331879, 2024). "Moreover, the tyrosine kinase receptor AXL was identified as a ST3GAL1 substrate, which is fundamental for the pro-invasive effects of ST3GAL1 in melanoma cells." (PMID 34440905, 2021). "Further, this study shed light on the regulation of ST3GAL1 in melanoma cells." (PMID 34440905, 2021). "Our study reveals a functional ST3GAL1-AXL axis driving melanoma metastasis and suggests that inhibition of this axis may become in the future a promising therapeutic strategy for metastatic melanoma." (PMID 33203881, 2020). "Importantly, we show that ST3GAL1 silencing in a highly invasive melanoma cell line reduces the number of melanoma cells able to enter the blood stream (circulating melanoma cells) and drastically diminishes metastatic dissemination to the lungs." (PMID 33203881, 2020). "Indeed, we found that ST3GAL1 is expressed at low levels in normal skin and nevi, and its expression increases during melanoma progression at both mRNA and protein levels." (PMID 33203881, 2020). "We first assessed whether ST3GAL1 plays a role in melanoma cell invasiveness using in vitro migration and invasion assays." (PMID 33203881, 2020). "Altogether these results indicate that ST3GAL1 endows melanoma cells with metastatic potential." (PMID 33203881, 2020). "Our study indicates that ST3GAL1 expression levels correlate with melanoma progression." (PMID 33203881, 2020).
melanoma (continued). "Using in vitro and in vivo studies, we demonstrate that ST3GAL1 drives melanoma metastasis." (PMID 33203881, 2020). "In addition, biochemical and functional studies reveal that the receptor tyrosine kinase AXL is a major mediator of the pro-invasive effects of ST3GAL1 in melanoma." (PMID 33203881, 2020). "We next asked whether the increased sialylation of the identified RTKs by ST3GAL1 could be relevant for their biological activation in melanoma." (PMID 33203881, 2020). "Modulation of the ST3GAL1–AXL axis may represent a target in melanoma treatment." (PMID 34683168, 2021). "In addition, ST3GAL1 depletion inhibits seeding of melanoma cells in several organs, suggesting that sialylation by ST3GAL1 may be required for the ability of melanoma cells to enter the blood stream, form metastases, and survive in a metastatic environment." (PMID 33203881, 2020). "However, we found that melanoma cells overexpressing ST3GAL1 give rise to larger metastases compared to control cells, suggesting that melanoma cells with high ST3GAL1 expression may have a better chance to strive and survive in “host” tissues." (PMID 33203881, 2020). "St3gal1 is a key negative regulator of Chimeric Antigen Receptor (CAR)-T cell cancer-specific migration and promotes melanoma invasion." (PMID 40896496, 2025). "Consistently, authors demonstrated that ST3GAL1 mediates SOX2- and GLI1-induced melanoma invasiveness." (PMID 33921986, 2021). "The western blot also elucidated that ST3GAL1, SOX2, GLI1, and AXL all have higher expression in metastatic melanomas as compared to primary melanomas." (PMID 35008286, 2021). "A recent study showed that in melanoma cells the oncogenic TFs SOX2 and GLI1 co-regulate ST3GAL1 transcription." (PMID 33921986, 2021). "Here, the authors report oncogenic SOX2-GLI1 transcriptional complex to drive melanoma invasion through the induction of the sialyltransferase ST3GAL1, and report ST3GAL1-AXL axis as driver of melanoma metastasis." (PMID 33203881, 2020). "Western blots showed that primary melanoma cells express lower levels of SOX2, GLI1, ST3GAL1, and AXL than metastatic melanoma cells, and that the latters harbor a stronger activation of SOX2/GLI1-ST3GAL1-AXL axis." (PMID 33203881, 2020). "Here we show that the sialyltransferase ST3GAL1 is transcriptionally regulated by both GLI1 and SOX2 in melanoma and is a crucial driver of melanoma cell invasiveness and melanoma metastasis in vivo." (PMID 33203881, 2020). "Though overexpression of ST3GAL1 did not result in increased ability to metastasize, ST3GAL1 is necessary for melanoma metastasis." (PMID 35008286, 2021). "Furthermore, protein levels of GLI1, SOX2, ST3GAL1, and AXL were analyzed in short-term cultures of primary and metastatic melanomas." (PMID 33203881, 2020). "Our data also indicate that overexpression of ST3GAL1 does not endow melanoma cells with increased ability to metastatize." (PMID 33203881, 2020). "Furthermore, ectopic expression of ST3GAL1 rescues the effect of SOX2 and/or GLI1 depletion on melanoma cell invasiveness." (PMID 33203881, 2020). "ST3GAL1 induces AXL dimerization and activation that, in turn, promotes melanoma invasion." (PMID 33203881, 2020). "Ectopic expression of ST3GAL1 did not affect the number of CTCs nor the number of micrometastases per lung compared to control, although mice injected with melanoma cells transduced with LV-ST3GAL1 exhibited higher number of macrometastases." (PMID 33203881, 2020). "In addition, ST3GAL1 is preferentially expressed in human melanomas compared to other types of skin cancer, such as BCC or SCC, which is consistent with the higher potential to metastasize of melanomas respect to other types of skin cancer." (PMID 33203881, 2020).
melanoma (continued). "Indeed, ST3GAL1 appears to mediate the effects of SOX2 and GLI1 on melanoma cell invasion." (PMID 33203881, 2020). "Next, we asked whether ST3GAL1 could mediate SOX2- and GLI1-induced melanoma invasiveness." (PMID 33203881, 2020). "Silencing of ST3GAL1 suppressed melanoma migration and invasion, and reduced the ability of aggressive melanoma cells to enter the bloodstream, colonize distal organs and survive in the metastatic environment, without affecting melanoma cell proliferation nor orthotopic tumor growth in vivo." (PMID 33921986, 2021). "However, no data are available on the role of ST3GAL1 in melanoma." (PMID 33203881, 2020). "Consistently, our data rule out the involvement of EGFR in mediating ST3GAL1-dependent cell migration and invasiveness and narrow that of NGFR in ST3GAL1-dependent melanoma cell migration." (PMID 33203881, 2020).
bladder cancer (5 papers, 2009 to 2023). "The overexpression of ST3GAL1 has been linked to a negative prognosis in various cancers, such as colorectal, breast, ovarian, and bladder cancer, and gliomas." (PMID 38067186, 2023). "P. Videira found mRNA level of ST3GAL-1 was significantly higher in malignant bladder tumor." (PMID 26552809, 2015). "The human bladder cancer (BC) cell line HT1376 strongly expressing the T antigen, was retrovirally transduced with the ST3GAL1 cDNA or with an empty vector, yielding the cell lines HT1376sT and HT1376T, that express, respectively, either the sT or the T antigens." (PMID 29454317, 2018).
glioma (5 papers, 2018 to 2025). A benign or malignant brain and spinal cord tumor that arises from glial cells (astrocytes, oligodendrocytes, ependymal cells). "Additionally, the study demonstrated that the transcriptomic program associated with ST3GAL1 is associated with a poor prognosis in glioma patients and results in higher tumor grades in the mesenchymal subtype." (PMID 38067186, 2023). "Interestingly, the authors observed a statistically significant association between low ST3GAL1 expression in low-grade gliomas and IDH1 mutations." (PMID 38067186, 2023). "show that the ST3GAL1-related transcriptome programs were indicators for an unfavorable prognosis in glioma patients, accompanied by higher tumor grade higher mesenchymal molecular grading." (PMID 35444644, 2022). "ST3GAL1 has been implicated in tumour progression and TMEM71 has been shown to be upregulated in gliomas." (PMID 36422592, 2022). "Interestingly, also in glioma cells, ST3GAL1 expression resulted in transcriptomic changes affecting malignancy and the cell cycle, supporting the notion that a carbohydrate structure on the cell surface can generate an “outside in” flow of information modulating gene expression." (PMID 29454317, 2018).
prostate carcinoma (5 papers, 2012 to 2025). A carcinoma that arises from epithelial cells of the prostate gland. "In contrast, ST3GAL1 modulates immune evasion in prostate cancer by synthesizing sialoglycans that interact with Siglec-7 and Siglec-9 receptors on immune cells." (PMID 39860532, 2025). "In prostate cancer, ST3Gal1 was shown to promote immune evasion by synthesizing α2,3‐sialylated ligands for Siglec‐7 and Siglec‐9 receptors on immunosuppressive macrophages, thereby disrupting anti‐tumor immunity." (PMID 40497576, 2025). "We conclude that the activity of ST3Gal1 is critical to prostate cancer anti-tumour immunity and provide rationale for the use of glyco-immune checkpoint targeting therapies in advanced prostate cancer." (PMID 38448753, 2024).
colon cancer (3 papers, 2014 to 2024). "The significance of ST3Gal1 in OVCA is unknown, but has been linked to colon cancer." (PMID 26879975, 2016). "They reported that, when EGF was used in colon cancer cell lines, glycosyltransferase, including FUT3, FUT6, and ST3GAL1/3/4, was elevated." (PMID 38528852, 2024). "In colon cancer SW488 cells, hypoxia induces expression of FUT7 and ST3GAL1, leading to overexpression of sialyl Lewis X antigen and hematogenous metastasis to liver via E-selectin." (PMID 24753248, 2014).
pancreatic cancer (3 papers, 2021 to 2022). "The comparison of human pancreatic cancer to the adjacent normal pancreas showed statistically significant increases for ST6GAL1 and ST3GAL1 in PDAC." (PMID 34634466, 2021).
benign meningioma (2 papers, 2021 to 2024). A grade I, slowly growing meningioma. "In the benign meningioma cell line, glycation led to differences in expression of sialyltransferases (ST3GAL1/2/3/5/6, ST6GAL1/2, ST6GALNAC2/6, and ST8SIA1/2), which are known to play a role in tumor progression." (PMID 34943806, 2021). "In the meningioma cell lines, mRNA expression of ST6GAL1 was highly expressed in the primary benign meningiomas—SUT-MG12 and SUT-MG14—while the mRNA expression of ST3GAL1 and ST3GAL3 was observed in the malignant meningioma cell lines—HKBMM and IOMM-Lee." (PMID 38274327, 2024).
colon adenocarcinoma (2 papers, 2024 to 2025). "For instance, tRFdb-3013a/b can target and regulate the expression of ST3GAL1 in colon adenocarcinoma, thereby exerting antitumor effects." (PMID 40153423, 2025). "Our bioinformatics analyses displayed the interaction relationships of tRFdb-3013a/b and their predicted target genes, and found that tRFdb-3013a/b could bind to the 3’UTR of ST3GAL1, which was highly expressed in colon adenocarcinomas." (PMID 38451187, 2024). "Additionally, the 3′UTR of ST3GAL1 mRNA was predicted to contain the binding site of tRFdb-3013a/b, tRFdb-3013a/b might directly target and regulate ST3GAL1 expression in colon adenocarcinomas." (PMID 38451187, 2024). "In addition, tRFdb-3013a over-expressions could down-regulate the expression levels of ST3GAL1 protein and mRNA in colon adenocarcinoma cells." (PMID 38451187, 2024). "Additionally, tRFdb-3013a/b could directly target the 3′UTR of ST3GAL1 and regulate ST3GAL1 expressions in colon adenocarcinomas." (PMID 38451187, 2024). "Moreover, the analysis of TCGA-COAD and GSE39582 data showed that ST3GAL1 was highly expressed in colon adenocarcinomas compare to non-tumor controls (both P <0.01) tRFdb-3013a and tRFdb-3013b were conversely decreased in colon adenocarcinomas." (PMID 38451187, 2024).
colorectal cancer (2 papers, 2015 to 2017). A primary or metastatic malignant neoplasm that affects the colon or rectum. "In colorectal carcinoma, ST3GAL-1 expression was associated with lymph node metastasis." (PMID 26552809, 2015).
E. coli infection (2 papers, 2025). "ST3GAL1 enhanced innate immunity against E. coli infection by activating the TLR signaling pathway in porcine intestinal epithelial cells during E. coli F18 infection." (PMID 41345738, 2025). "In addition, resistance to F18+ E. coli infection has been associated with multiple genetic loci including FUT1, FUT2, ST3GAL1, and B3GALNT." (PMID 39917050, 2025).
influenza (2 papers, 2010 to 2015). An acute viral infection of the respiratory tract, occurring in isolated cases, in epidemics, or in pandemics; it is caused by serologically different strains of viruses (influenzaviruses) designated A, B, and C, has a 3-day incubation period, and usually lasts for 3 to 10 days. "In the present study, two polymorphisms of the ST3GAL1 gene, which encodes the Siaα2-3Galβ1- receptor, were investigated in patients with a diagnosis of influenza caused by the pandemic strain." (PMID 26436774, 2015). "In particular, the generation of influenza-specific humoral responses is impaired in mice lacking ST6GAL1, while ST3GAL1 regulates apoptosis of CD8+ T cells." (PMID 20174570, 2010).